IFNAR1 (interferon alpha and beta receptor subunit 1)
Diseases named in the same sentence as IFNAR1 in open-access papers (continued):
Sharing a sentence is not in itself a finding about the gene and the disease.
systemic sclerosis (3 papers, 2014 to 2021). A chronic disorder, possibly autoimmune, marked by excessive production of collagen which results in hardening and thickening of body tissues. "In this study they also report that IFNAR1 is upregulated in Systemic Sclerosis patients with PH and that Interferon Regulated Protein 10 (IP10) correlated positively with pulmonary hemodynamics and serum brain natriuretic peptide and negatively with 6-minute walk test and cardiac index." (PMID 24837600, 2014). "Also in a model of systemic sclerosis (Ssc) -like cutaneous GVHD, protection was achieved by blocking type I IFN signaling via usage of a neutralizing Ab against IFNAR1." (PMID 34249014, 2021).
acute pancreatitis (2 papers, 2014 to 2015). An acute inflammatory process that leads to necrosis of the pancreatic parenchyma. "We initially focused on the role of IFN signaling and IFNAR1 stability in development of acute pancreatitis, a deadly disease affecting millions of people worldwide [reviewed in]." (PMID 24480543, 2014). "Remarkably, wild type (Ifnar1+/+) and Ifnar1−/− mice displayed a similar severity of these alterations suggesting that either IFN signaling plays no role in pathogenesis of acute pancreatitis or IFNAR1 is inactivated under these conditions in wild type tissues." (PMID 24480543, 2014).
amyloid (2 papers, 2016 to 2025). "Our observation that removal of IFNAR1 in APPSWE/PS1ΔE9 mice alters many aspects of the neuro-inflammatory response, improves performance in the MWM behavioural test paradigm, but does not significantly alter amyloid pathology is notable." (PMID 27400725, 2016).
asthma (2 papers, 2014 to 2024). "However, the induction of several interferon-related genes (IRF3, IFNAR1, IFNB1, IFNGR1, IL28B) was impaired in patients with asthma." (PMID 24475887, 2014). "Among the genes that were induced in all subjects except for patients with asthma were interferon involved genes (IL28B, IFNAR1), CCL22, and FOSL1 with respect to the upper airways, and several interferon involved genes (IRF3, IFNAR1, IFNB1, IFNGR1, IL28B) in the lower airways." (PMID 24475887, 2014).
brain injury (2 papers, 2020 to 2023). Acute and chronic (see also brain INJURIES, CHRONIC) injuries to the brain, including the cerebral hemispheres, CEREBELLUM, and brain STEM. "However, the finding that SYP+ presynaptic terminals are only partially protected and primarily in females, and spatial memory is only normalized in females suggests a crucial role for other, sex-dependent, and IFNAR1-dependent factors in HIV-induced brain injury that remain to be elucidated." (PMID 32727588, 2020).
colorectal adenocarcinoma (2 papers, 2018 to 2022). The most common type of colorectal carcinoma. "Midostaurin increased mRNA expressions of cGAS, IRF3, and IFNAR1 in colorectal adenocarcinoma cells and mouse spleen macrophages." (PMID 36230769, 2022). "Midostaurin inhibited colorectal adenocarcinoma cell growth associated with the formation of dsDNA and ssDNA; the up-regulation of mRNA expression of cGAS, STING, IRF3, and IFNAR1; the down-regulation of Trex-1, c-Kit, and Flt3 protein expression." (PMID 36230769, 2022).
depression (2 papers, 2022 to 2024). "RNA editing shows a strong association with interferon response, and polymorphisms in the promoter region of IFNAR1 have been linked to increased depression risk." (PMID 39684694, 2024). "RNA editing is strongly linked to interferon response, and polymorphisms in the promoter region of IFNAR1 can influence the risk of developing depression." (PMID 35504874, 2022). "RNA editing modifications were analyzed using a panel of eight genes (CAMK1D, GAB2, IFNAR1, KCNJ15, LYN, MDM2, PDE8A, PRKCB) that we previously identified and whose editing combinations were suggested as biomarkers to distinguish BD from unipolar depression and subcategories of BD patients." (PMID 39684694, 2024).
dermatitis (2 papers, 2017 to 2021). An inflammatory process affecting the skin. "Indeed, IFNAR1 deficiency rescued ΔKerOTULIN mice from dermatitis development in about 60% of the mice." (PMID 34625556, 2021). "A more recent study, however, indicates that erythema, epidermal proliferation, and splenomegaly are reduced in IMQ dermatitis of Ifnar1-KO mice (B6)." (PMID 28279190, 2017).
fungal infection (2 papers, 2011 to 2015). "We found that Ifnar1-/- mice are highly susceptible to H99, and furthermore, triggering type I IFN through the administration of pICLC induced multiple immunological changes leading to a profound resistance to this fungal infection." (PMID 26252005, 2015).
glomerulonephritis (2 papers, 2016 to 2025). A renal disorder characterized by damage in the glomeruli. "In the Ifnar1 KO T cell-transferred group, mice developed less severe glomerulonephritis compared to WT T cell-transferred group." (PMID 40393992, 2025). "In contrast, there was a partial reduction in the extent of glomerulonephritis in ABIN1[D485N] × IFNAR1-KO mice compared with ABIN1[D485N] mice." (PMID 27807192, 2016).
H1N1 virus infection (2 papers, 2010 to 2025). "To further validate the downregulation of key IFN-related genes identified in the transcriptomic analysis, we assessed the mRNA expression levels of selected antiviral genes in WT and IFNAR1-KO cells following H1N1 virus infection." (PMID 40872812, 2025).
HCMV infection (2 papers, 2021 to 2023). "IFN treatment showed an obvious inhibitory effect against viral reactivation; however, IFN treatment failed to reduce latent HCMV infection in THP-1 cells but did alter the expression of IFNAR1." (PMID 33746965, 2021).
head and neck squamous cell carcinoma (2 papers, 2019 to 2021). A squamous cell carcinoma that arises from any of the following anatomic sites: lip and oral cavity, nasal cavity, paranasal sinuses, pharynx, larynx, and salivary glands. "The activation of IFNAR1/STAT1 signaling in head and neck squamous cell carcinoma (HNSCC) by IFN-α is associated with the establishment of an immunosuppressive microenvironment favoring the expression of PD-L1 in HNSCC cells, PD-1 in immune cells and impairs the lithic activity of NK cells." (PMID 34571790, 2021). "We examine the expression of interferon alpha/beta receptor-1 (IFNAR1), CD8, CD56 and programmed death ligand 1 (PDL1) in head and neck squamous cell carcinomas (HNSCC)." (PMID 30555157, 2019).
hepatitis C (2 papers, 2015 to 2025). "IFNAR1 inhibition modulated the expression of genes involved in cytokine interactions, drug metabolism, hepatitis C, macrophage activation, innate immune regulation, the PI3K-AKT pathway, and chemical carcinogenesis." (PMID 40260261, 2025). "Reduced expression of IFNAR1 has also been observed in the liver biopsies of chronic liver disease patients with hepatitis C virus infection." (PMID 25961570, 2015). "Notably, hepatitis C-related genes were also significantly altered, with upregulation and downregulation observed in the CCl4+IFNAR1 group." (PMID 40260261, 2025).
interstitial lung disease (2 papers, 2025). A diverse group of lung diseases that affect the lung parenchyma. "We previously demonstrated that interstitial lung disease developed largely independent of the IFN I signaling, and occurs in the absence of cGAS, IRF3, IRF7, and of IFNAR1." (PMID 40111902, 2025).
intrauterine growth restriction (2 papers, 2017 to 2020). "Infection of Ifnar1−/− dams mated with wt males resulted in fetal demise, while when pregnant wt dams were given anti-IFNAR mAb prior to and during infection, there was mild intrauterine growth restriction (IUGR) and viral infection within the fetal head during a key period of neurodevelopment." (PMID 28608813, 2017).
ischemic stroke (2 papers, 2015 to 2023). A stroke disorder caused by obstruction of blood flow to the brain, due to thrombotic (local blood clot formation) or embolic (due to a blood clot or other material traveling from another site) event. "First, further studies would be required to identify the signaling pathways activated by IFNβ/IFNAR1 axis modulating MG polarization in delayed tPA-treated ischemic stroke." (PMID 37063896, 2023). "Studies have shown that interferon beta (IFNβ) or type I IFN receptor (IFNAR1) signaling confers protection against ischemic stroke in preclinical models." (PMID 37063896, 2023). "Collectively, our results demonstrate that IFNβ-induced IFNAR1 signaling activation in MG plays an essential role in conferring protection against delayed tPA-exacerbated brain injury in ischemic stroke." (PMID 37063896, 2023). "In addition, studies from other groups showed that IFNβ and/or type I IFN receptor (IFNAR1) signaling confer protection against brain injury in ischemic stroke animal models." (PMID 37063896, 2023). "Notably, the effects of IFNβ on modulating MG phenotypes and ameliorating delayed tPA-exacerbated brain injury in ischemic stroke were abolished in mice with the conditional knockdown of IFNAR1 in MG." (PMID 37063896, 2023). "Further studies of silencing STAT3 specifically in MG would provide insight into whether the activation of STAT3 via IFNAR1 signaling is required for IFNβ-mediated modulation of MG phenotypes in ischemic stroke with delayed tPA treatment." (PMID 37063896, 2023). "Since we observed IFNβ modulated MG phenotypes and ameliorated brain injury in delayed tPA-treated MCAO mice, we thought to assess whether IFNβ-mediated activation of IFNAR1 signaling in MG plays an essential role in ameliorating delayed tPA-exacerbated brain injury in ischemic stroke." (PMID 37063896, 2023). "Altogether, our results demonstrate that the knockdown of IFNAR1 specifically in MG abolishes IFNβ-mediated modulation of MG phenotypes that may subsequently abrogate the protective effect of IFNβ on the amelioration of delayed tPA-exacerbated brain injury in ischemic stroke." (PMID 37063896, 2023). "Thus, further studies using conditional knockout mice in which IFNAR1 is specifically knockout in brain endothelial cells are warranted to elucidate the direct effect of IFNβ on modulating brain endothelial cells to lessen delayed tPA-aggravated BBB disruption in ischemic stroke." (PMID 37063896, 2023).
leukemia (2 papers, 2023 to 2024). A malignant (clonal) hematologic disorder, involving hematopoietic stem cells and characterized by the presence of primitive or atypical myeloid or lymphoid cells in the bone marrow and the blood. "Accordingly, STAT3β-deficient leukemia cells displayed enhanced sensitivity to blockade of IFN signaling through both an IFNAR1 blocking antibody and the JAK1/2 inhibitor Ruxolitinib." (PMID 38806478, 2024). "Using an IFNα receptor 1 (IFNAR1) blocking antibody or IgG1 control, we compared leukemia development in Usp18+/f and Usp18+/Δ AE9a recipients." (PMID 36646704, 2023).
liver cancer (2 papers, 2023 to 2024). An epithelial or non-epithelial malignant neoplasm that arises from the liver. "The level of IFN-I-stimulated genes was related to the poor efficacy of ICB in patients of melanoma or breast cancer, and anti-IFNAR-1 antibody overcame the drug resistance of anti-PD1 antibody in mouse liver cancer." (PMID 37398660, 2023).
lung fibrosis (2 papers, 2020 to 2024). "Ifnar1-/- mice did not display enhanced lung cell influx and lung fibrosis as shown by representative lung histology and Ascroft fibrosis score and the expression of the extracellular matrix protein fibronectin (Fn1)." (PMID 33488589, 2020).
mental disorder (2 papers, 2023 to 2024). A disease that has its basis in the disruption of mental process. "Emerging research suggests that IFNAR1 dysregulation and the resulting impact on type I IFN signaling can influence the pathophysiology of several mental disorders via neuroinflammation." (PMID 39684694, 2024).
narcolepsy (2 papers, 2017 to 2020). A sleep disorder characterized by a tendency for excessive sleepiness during the day which occurs even after adequate sleep in the nighttime. "Thus, IFNAR1 may serve as a novel target for immune therapy of narcolepsy in the future." (PMID 32669953, 2020).
pancreatic adenocarcinoma (2 papers, 2024). "Pancreatic adenocarcinoma tumors exhibit increased levels of mRNA expression for components of the Transforming growth factor-β pathway (TGFB1/2/3, TGFBR1/2/3) and Interferon Type I pathways (IFNAR1, STAT1, IRF9 and IFI27)." (PMID 39457004, 2024).
polyarthritis (2 papers, 2009 to 2015). "Note added in proof: While this manuscript was under review, Ellen Gravallese and colleagues have published a likewise approach of studying the role of AIM2 in the context of Dnase2-/- x Ifnar1-/- induced polyarthritis." (PMID 26114879, 2015).
Rickettsiosis (2 papers, 2021 to 2025). A group of infectious diseases that is caused by Rickettsia. "We previously reported that Ifnar1−/−; Ifngr1−/− DKO mice, carrying mutations in the genes encoding the receptors for IFN-I (Ifnar1) and IFN-γ (Ifngr1), are susceptible to eschar-associated rickettsiosis." (PMID 39819005, 2025). "Thus, Ifnar1-/-;Ifngr1-/- mice are a tractable model to investigate rickettsiosis, virulence factors, and immunity." (PMID 34423779, 2021).
Rotavirus infection (2 papers, 2021 to 2022). Infection with any of the rotaviruses. "In agreement with earlier studies, we observed that animals lacking functional receptors for type I IFN (Ifnar1-/-), for type III IFN (Ifnlr1-/-) or for both IFN types (DKO) were more susceptible to rotavirus infection compared with WT mice." (PMID 34383769, 2021).
Salmonella Infections (2 papers, 2014 to 2016). Infections with bacteria of the genus SALMONELLA. "All together, our findings demonstrate that IFNAR1-mediated signaling can inhibit the host antimicrobial response to Salmonella infection." (PMID 27149619, 2016).
scrub typhus (2 papers, 2018 to 2024). Scrub typhus is a rare dust mite-borne infectious disease caused by the Orientia tsutsugamushi bacterium and characterized clinically by an eruptive fever which is potentially serious. "Using double Ifnar1-/-Ifngr1-/- and Stat1-/- mice, we found that deficiency in IFN/STAT1 signaling resulted in lethal infection with profound pathology and skin eschar lesions, which resembled to human scrub typhus." (PMID 38743761, 2024). "In contrast, both double Ifnar1-/-Ifngr1-/- and Stat1-/- mice displayed evident skin lesions marked by necrosis of the overlying epidermis and hardening features, surrounded by an indurated red halo (red arrows), which resembled skin eschars in scrub typhus patients." (PMID 38743761, 2024).
vasculitis (2 papers, 2021 to 2025). "In Ifnar1-/-;Ifngr1-/- mice, we observed necrosis, vasculitis, fibrin thrombi, and rickettsial staining that coincided primarily with infiltrating macrophages and neutrophils." (PMID 34423779, 2021).
visceral leishmaniasis (2 papers, 2018 to 2024). A severe form of leishmaniasis characterized by irregular bouts of fever, substantial weight loss, swelling of the spleen and liver, and anemia (which may be serious). "In visceral leishmaniasis (VL) caused by L. donovani, IFNα/β acts as an upstream suppressor of anti-parasitic TH1 cells, and IFNAR1 −/− mice better control infection compared to wild type 32." (PMID 38746226, 2024).
abscesses (1 paper, 2012). "However, at day 3, Ca-containing abscesses were still abundantly present in WT mice but were mainly cleared in IFNAR1-deficient animals." (PMID 22911155, 2012).
Acute hepatitis (1 paper, 2021). Acute hepatic injury resulting from inflammation typically accompanied by increased serum alanine transaminase activity. "By contrast, infection resulted in the upregulation of hundreds of genes in Ifnar1-/- mice that develop acute hepatitis closely modeling human disease." (PMID 34591933, 2021).
alopecia (1 paper, 2025). Hair loss usually from the scalp. "Biologics, including TNF-α, IL-17, IL-23, IFNAR1 inhibitors, as well as JAK inhibitors, may represent a new frontier in the treatment of scarring alopecias refractory to the standard of care by modulating key inflammatory pathways." (PMID 40488905, 2025).
anaphylaxis (1 paper, 2019). An acute hypersensitivity reaction that occurs from exposure to an allergen. "When WT mice were treated with the anti-IFNAR1 antibody, they exhibited more severe hypothermia in association with IgE-mediated systemic anaphylaxis compared with control mice, and the severity of the hypothermia increased as greater amounts of anti-IFNAR1 antibodies were injected." (PMID 31730616, 2019). "We also examined local anaphylaxis using the passive cutaneous anaphylaxis (PCA) model and found that the endothelial permeability was increased in the Ifnar1−/− mice." (PMID 31730616, 2019).
aneurysm (1 paper, 2022). Bulging or ballooning in an area of an artery secondary to arterial wall weakening. "IFNAR1 deficiency was associated with reduced incidence and progression of experimental AAAs following aneurysm induction." (PMID 36291750, 2022). "In conclusion, IFNAR1 appears to play a role in experimental aneurysm formation and progression." (PMID 36291750, 2022).
Anorexia (1 paper, 2017). Lack of desire to eat (loss of appetite). "Using IFN-I receptor 1 (IFNAR1)-deficient mice, the results of the authors present suggest that IFN-I are involved in the induction of sickness behavior, including anorexia, whereas IL-6 participates in sickness behavior but not in anorexia." (PMID 28855891, 2017).
aortic aneurysm (1 paper, 2022). A ruptured aneurysm located in the wall of the proximal portion of the descending aorta proceeding from the arch of the aorta. "In the present study, both human AAA surgical specimens and mice deficient for IFNAR1 were employed to examine the role of type I IFN activity in aortic aneurysm pathogenesis." (PMID 36291750, 2022).
avian influenza (1 paper, 2022). Infection of domestic and wild fowl and other birds with influenza A virus. "We further investigated the role or IFNAR1 on low pathogenicity avian influenza (LPAI) strains (H7N9) and a HPAI strain (H5N1)." (PMID 35056582, 2022).
bone cancer (1 paper, 2021). A primary or metastatic malignant neoplasm affecting the bone or articular cartilage. "Therefore, host IFN-I signaling through Ifnar1 is required for the protective effects of STING agonists on cancer pain and bone destruction induced by bone cancer." (PMID 34315904, 2021). "Thus, systemic administration of STING agonists reduces local bone cancer tumor burden in a STING- and Ifnar1-dependent manner." (PMID 34315904, 2021). "To test how IFN-I signaling contributes to the protective effects of STING agonists in the bone cancer model, we again introduced LLC cells into the femora of Ifnar1+/+ (WT) or Ifnar1−/− (KO) mice to establish the bone cancer models in mice with deficient host IFN-I signaling." (PMID 34315904, 2021). "To further determine whether neuronal IFN-I signaling is responsible for the acute antinociceptive effects of STING agonists, we established the bone cancer pain model using mice lacking Ifnar1 selectively in sensory neurons (Ifnar1fx/fx; Nav1.8-Cre; Ifnar1-cKO), or their wildtype littermates." (PMID 34315904, 2021).
Cachexia (1 paper, 2015). Severe weight loss, wasting of muscle, loss of appetite, and general debility related to a chronic disease. "However, weight loss occurred rapidly in IFNAR1−/− mice and therefore must be independent of IFN-I, perhaps occurring via TNF-α, which is known to contribute to cachexia and whose expression is increased by poly I:C and not significantly diminished in IFNAR1−/− mice." (PMID 25900439, 2015).
cardiac hypertrophy (1 paper, 2025). "Compared with those in the control mice, both C-176 and IFNAR1 antibody treatment prevented Nap1l1 p.D349E-mediated cardiac hypertrophy and fibrosis." (PMID 40169585, 2025).